ZNF567 (zinc finger protein 567)
Description:
May be involved in transcriptional regulation.
Synonyms: MGC45586
Tractability: PROTAC: UniProt records ubiquitination sites on it; ubiquitination databases record sites on it.
Gene: Protein-coding gene on chromosome 19 (36,687,268 to 36,727,701, forward strand). Ensembl gene ENSG00000189042.
Subcellular location: Nucleus
Subcellular location (Human Protein Atlas): Nucleoplasm; Cytosol
Pathways (Reactome):
Gene expression (Transcription): Generic Transcription Pathway
Gene Ontology:
Molecular function: protein binding; DNA-binding transcription factor activity; RNA polymerase II cis-regulatory region sequence-specific DNA binding
Biological process: regulation of transcription by RNA polymerase II; regulation of DNA-templated transcription
Cellular component: nucleus
Genetic constraint (gnomAD): Loss-of-function variants: 36 observed, 54.22 expected, observed/expected ratio (o/e) 0.66, 90% interval 0.51 to 0.88. The upper end of that interval is the gene's LOEUF score, 0.88, which puts it in group 3 of 6, group 1 being the genes least tolerant of losing a copy. Missense variants: 612 observed, 798.45 expected, observed/expected ratio (o/e) 0.77, 90% interval 0.72 to 0.82. Synonymous variants: 224 observed, 273.94 expected, observed/expected ratio (o/e) 0.82, 90% interval 0.73 to 0.91.
Homologues: Orthologues: chimpanzee ZNF567 (99% identical), macaque ZNF567 (98% identical), dog ZNF567 (92% identical), rabbit ZNF567 (92% identical), pig ZNF567 (90% identical), guinea pig ZNF567 (77% identical), Drosophila melanogaster CG14442 (5% identical), Drosophila melanogaster CG14440 (3% identical). Paralogues in human: ZNF382 (52% identical), ZNF613 (39% identical), ZNF564 (35% identical), ZNF649 (35% identical), ZNF350 (33% identical), IKZF1 (14% identical), IKZF4 (14% identical), IKZF2 (13% identical), ZNF639 (13% identical), IKZF3 (12% identical), ZNF821 (8% identical).
Diseases named in the same sentence as ZNF567 in open-access papers:
ZNF567 is named in the same sentence as 1 disease in open-access papers, as found by Europe PMC text mining. Sharing a sentence is not in itself a finding about the gene and the disease. The quoted sentences say what the papers report.
tumor (1 paper, 2019). "Several genes splicing events, including KIAA1715/56096/AP, ZNF567/49415/AP, NTMT1/87861/AP, ANAPC15/17570/AD, SRPK2/81284/ES, MTMR11/7413/AP, FNIP2/70999/AP, and TNC/87336/ES, differed significantly between tumor and normal samples." (PMID 31552163, 2019).